PHF8 (PHD finger protein 8)
Diseases named in the same sentence as PHF8 in open-access papers (continued):
Sharing a sentence is not in itself a finding about the gene and the disease.
melanoma (continued). "Consistent with our findings in TCGA and in melanoma cell lines, we observed that while primary samples were similarly split between no/low and high PHF8 expression, most metastatic samples expressed high PHF8 levels, both in percentage of positive cells and staining intensity." (PMID 35179962, 2022). "For example, PHF8 directly controls the TGF-β signaling pathway, thus leading to melanoma invasion and metastasis." (PMID 37454216, 2023). "Among the genes directly modulated by PHF8, we found TGFβ-induced (TGFBI), a secreted extracellular matrix component that confers high metastatic potential to melanoma cells." (PMID 35179962, 2022). "On the other hand, PHF8 knockdown did not affect the proliferation of melanoma cells in vitro or xenograft tumor growth in vivo, but significantly reduced melanoma cells’ invasive capacity." (PMID 40940894, 2025). "We conclude that PHF8 enhances melanoma metastatic progression without affecting primary tumor growth." (PMID 35179962, 2022). "The loss of invasive capacity observed upon PHF8 knockdown in SKMEL-147 melanoma cells was consistently reproduced using the CRISPR-Cas9 system and two efficient small guide RNAs (sgRNAs) targeting PHF8 (sgPHF8 #1 and sgPHF8 #3) in four melanoma cell lines (SKMEL-147, 501Mel, A375, and 451Lu)." (PMID 35179962, 2022). "Accordingly, only PHF8 WT, and not the mutants lacking demethylase activity, was able to rescue the defect in invasion observed in PHF8 knockout melanoma cells." (PMID 35179962, 2022). "To better understand mechanisms of melanoma metastasis, we opted to focus on PHF8, the modulation of which affected invasion without altering cell proliferation." (PMID 35179962, 2022). "S3), PHF8 does not regulate cell cycle progression in melanoma." (PMID 35179962, 2022).
neuroblastoma (6 papers, 2010 to 2024). Neuroblastoma (NB) is the most common solid, extracranial childhood tumor. "We studied underlying molecular mechanisms by manipulating Blmh or Phf8 expression or Hcy-thiolactone and N-Hcy-protein levels in mouse neuroblastoma N2a-APPswe cells." (PMID 37718819, 2023). "Notably, Pon1 depletion caused changes in the Phf8- > H4K20me1- > mTOR- > autophagy pathway akin to the changes induced by HHcy in the mouse brain and neuroblastoma cells." (PMID 36899882, 2023). "Pon1 depletion downregulated Phf8 and upregulated Aβ in the brains of Pon1−/−5xFAD mice and in mouse neuroblastoma N2a-APPswe cells." (PMID 39125665, 2024). "To elucidate the mechanism by which Blmh depletion impacts Phf8 and its downstream effects on mTOR, autophagy, and AβPP, we first examined whether our findings in Blmh-/- mice can be recapitulated in cultured mouse neuroblastoma N2a-APPswe cells carrying a mutated human AβPP transgene." (PMID 37718819, 2023). "These include controlling subcellular localization of PTEN to promote AML progression, stabilization of the histone demethylase PHF8 to promote breast carcinogenesis, and stabilization of N‐Myc to promote neuroblastoma progression, among others." (PMID 34469054, 2021). "The study showed that Pon1 depletion, which causes the accumulation of Hcy-thiolactone and the N-Hcy-protein in mice, downregulated the histone demethylase Phf8 and upregulated the H4K20me1 epigenetic mark in brains of Pon1−/− mice and in Pon1-silenced mouse neuroblastoma N2a-APPswe cells." (PMID 39125665, 2024). "Our present findings that Phf8 depletion in mouse neuroblastoma cells, induced by Phf8 gene silencing or by supplementation with Hcy-thiolactone or N-Hcy-protein, significantly increased Aβ accumulation, suggest that Phf8 depletion can also underly the association of HHcy with AD." (PMID 37718819, 2023). "We found that Blmh depletion downregulated Phf8 in mouse brain and mouse neuroblastoma cells, upregulated AβPP in mouse brain and mouse neuroblastoma cells, and Aβ in mouse brain and mouse neuroblastoma cells." (PMID 37718819, 2023). "Blmh and Phf8 genes were silenced in mouse neuroblastoma N2a-APPswe cells by RNA interference." (PMID 37718819, 2023). "Indeed, as we also found in the present study, treatments with Hcy-thiolactone or N-Hcy-protein induce changes in the Phf8->H4K20me1->mTOR->autophagy pathway and Aβ accumulation in mouse neuroblastoma cells like those seen in Blmh-/- mice or mice fed with high Met diet." (PMID 37718819, 2023). "The findings that Phf8 expression was significantly reduced in the brains of Blmh-/- and Blmh-/-5xFAD mice and in the Blmh-silenced or Hcy metabolite-treated mouse neuroblastoma N2a-APPswe cells, suggested that Phf8 depletion by itself can affect biochemical pathways leading to Aβ accumulation." (PMID 37718819, 2023). "Specifically, we found that Pon1 depletion downregulated histone demethylase Phf8 both at the protein and mRNA level, increased H4K20me1 binding at the mTOR promotor, and upregulated mTOR expression and phosphorylation in the mouse brain and neuroblastoma N2a-APPswe cells." (PMID 36899882, 2023). "To elucidate the mechanism by which Pon1 depletion impacts Phf8 and its downstream effects on mTOR, autophagy, and APP, we first examined whether the findings in Pon1−/− mice can be recapitulated in cultured mouse neuroblastoma N2a-APPswe cells that overproduce Aβ from a mutated human APP transgene." (PMID 36899882, 2023). "Given the fact that high‐grade neuroendocrine carcinomas including neuroblastoma, NEPC, and small‐cell carcinomas of the lung and bladder are all more aggressive, we wanted to determine if PHF8 plays any role in the tumor growth and invasiveness of NEPC." (PMID 33009820, 2021). "Although Pon1 depletion in mouse neuroblastoma N2a-APPswe cells downregulated Phf8 and upregulated APP and Aβ, depletion of Phf8 upregulated Aβ but not APP." (PMID 36899882, 2023).
Anxiety (5 papers, 2017 to 2024). Intense feelings of nervousness, tension, or panic often arise in response to interpersonal stresses. "Loss of Phf8 only confers resistance to depression-like and anxiety-like behaviors in mice and causes deficient learning and memory by epigenetic disruption of mTOR signaling." (PMID 36672913, 2023). "This assay revealed that Phf8 mutant mice spend significantly less time in the closed arms and more time in the open arms, supporting the notion that loss of Phf8 leads to a decrease in anxiety." (PMID 28485378, 2017). "Adverse concomitants, such as speech and developmental delays, psychomotor disorders, sensory abnormalities, autism, attention-deficit hyperactivity disorder (ADHD), anxiety, and violent behavior were observed in 11 variants and 16 individuals affected by the predictive loss of PHF8 function." (PMID 39311138, 2024). "Notably, Phf8 deficient animals display resilience to anxiety- and depression-related behavioural abnormalities, which uncovers a novel biological role for PHF8 not previously associated with this histone demethylase." (PMID 28485378, 2017). "A recent paper reported that a different strain of Phf8-deficient mice showed resilience to stress induced anxiety- and depression-related behavior and no intellectual disability." (PMID 29317619, 2018). "Our results clarify the functional role of Phf8 in mammalian development and behaviour and establish a direct link between Phf8 expression and serotonin signalling, identifying this histone demethylase as a potential target for the treatment of anxiety and depression." (PMID 28485378, 2017). "Our results raise the possibility that PHF8 is also involved in controlling anxiety and depression in humans and may thus represent a novel drug target." (PMID 28485378, 2017). "This assay showed that Phf8 KO mice are more active than WT controls within the first 15 min of the assessment and spend more time in the centre of the chamber, suggesting reduced anxiety." (PMID 28485378, 2017). "Altogether, these data indicate that Phf8 KO mice have a remarkable resiliency to anxiety- and depression-like behaviours using several independent stress-inducing paradigms, thus uncovering a biological role for PHF8 not previously associated with this histone demethylase." (PMID 28485378, 2017). "For instance, they did not detect decreased anxiety and depression in light–dark box assay and tail suspension test after Phf8 KO." (PMID 35941644, 2022). "We find that Phf8 null mice display neither developmental nor cognitive defects, but instead are resistant to anxiety- and depression-like behaviours." (PMID 28485378, 2017).
depression (4 papers, 2017 to 2023). "Here, the authors show that Phf8 deletion in mice causes no overt developmental defects but confers resilience to depression, likely through increased serotonin signalling." (PMID 28485378, 2017). "Given the cleaner expression data of the prefrontal cortex and the well-established link between serotonin signalling and depression, we focused on the molecular mechanisms by which Phf8 may perturb serotonin signalling in the prefrontal cortex in the remainder of this study." (PMID 28485378, 2017).
acute lymphoblastic leukemia (3 papers, 2013 to 2024). Leukemia with an acute onset, characterized by the presence of lymphoblasts in the bone marrow and the peripheral blood. "Furthermore, it has been reported that PHF8 is key regulator of oncogenic functions of NOTCH1 signaling in T cell acute lymphoblastic leukemia (T-ALL), which is also dependent on its KDM activity." (PMID 24146981, 2013).
acute promyelocytic leukemia (3 papers, 2013 to 2024). An aggressive form of acute myeloid leukemia (AML), characterized by arrest of leukocyte differentiation at the promyelocyte stage, due to a specific chromosomal translocation t(15;17) in myeloid cells. "Very recently, we demonstrated that the enzymatic activity of PHF8 is linked to the retinoic acid sensitivity in acute promyelocytic leukemia (APL)." (PMID 24146981, 2013). "PHF8 enzymatic function is critical to the mechanism of all-trans retinoic acid treatment in acute promyelocytic leukemia." (PMID 25340776, 2014).
attention deficit-hyperactivity disorder (3 papers, 2023 to 2024). A disorder characterized by a marked pattern of inattention and/or hyperactivity-impulsivity that is inconsistent with developmental level and clearly interferes with functioning in at least two settings (e.g. at home and at school). "Plant homeodomain finger protein 8 (PHF8) has been identified as one of the X chromosome genes linked to intellectual disability syndrome, autism spectrum disorder, attention deficit hyperactivity disorder, and severe mental retardation." (PMID 37718819, 2023).
liver cancer (3 papers, 2023 to 2024). An epithelial or non-epithelial malignant neoplasm that arises from the liver. "Sponge adsorption of miR-361-3p drives the expression of PHF8 in liver cancer to promote cancer progression and regulate drug sensitivity to sorafenib via autophagy." (PMID 39311138, 2024). "MiR-383 can reduce the PHF8 mRNA level to inhibit the proliferation, migration, and invasion of liver cancer cells." (PMID 39311138, 2024). "Also, PHF8 functions as an oncogene during liver cancer pathogenesis through increasing the expression of Cullin 4A (CUL4A), a regulator of EMT." (PMID 39311138, 2024).
ovarian cancer (3 papers, 2018 to 2022). A primary or metastatic malignant neoplasm involving the ovary. "Moreover, the p38/JNK pathways seem to be involved in histone lysine demethylase PHF8-mediated CCL7 expression in macrophages stimulated by ovarian cancer cells." (PMID 34206004, 2021). "The interaction of SOX-2 with PHF20L1 has already been demonstrated by others; SOX-2 and PHF8, another PHD finger protein, have been analyzed in ovarian cancer tumor tissues, showing that SOX-2 was overexpressed in mucinous carcinoma." (PMID 34991589, 2022). "Three affected genes, HUWE1, PHF8 and KLF8, are related to breast or ovary cancers." (PMID 29558483, 2018).
adenocarcinomas of the prostate (2 papers, 2016 to 2021). "In addition, we investigated the association of the expression of PHF8 and FOXA2 with pathological grade (Gleason scores) in 42 specimens with prostate adenocarcinoma." (PMID 33009820, 2021). "Since knocking out Phf8 had minimal effect on the initiation and progression of prostate adenocarcinoma but abrogated both the initiation and the metastasis of NEPC, we conclude that PHF8 plays a unique role in NEPC development." (PMID 33009820, 2021). "The co-expression of PHF8 with AR in clinical CRPC samples, normal mouse prostate, and adenocarcinomas of the prostate during PCa progression in a transgenic (TRAMP) mouse model supports the connection between PHF8 and AR." (PMID 27689328, 2016).
Alzheimer disease (2 papers, 2015 to 2024). A progressive, neurodegenerative disease characterized by loss of function and death of nerve cells in several areas of the brain leading to loss of cognitive function such as memory and language. "Clinically, mutations in PHF8 cause X-linked mental retardation while TIP60 has been implicated in the pathogenesis of Alzheimer’s disease." (PMID 26464965, 2015). "Specifically, demethylation of the transcriptionally suppressive H3K9me2 mark is linked to the acetylation of H3 through a specific interaction between the H3K9me2-specific X-linked mental retardation protein PHF8 and the Alzheimer’s disease-associated TIP60." (PMID 26464965, 2015).
cardiac hypertrophy (2 papers, 2019 to 2022). "While LSD1/KDM1A and PHF8/KDM7B have a protective effect on cardiac hypertrophy." (PMID 36523510, 2022).
chronic myeloid leukemia (2 papers, 2025). "Feng et al39 found that the expression level of PHF8 (PHD finger protein 8) was significantly elevated in chronic myeloid leukemia and was associated with a poor prognosis of the patients." (PMID 40584293, 2025). "The results suggest that PHF8 promotes the development of chronic myeloid leukemia by directly regulating the expression of the BCR-ABL1 gene through demethylation." (PMID 40584293, 2025). "PHF8 showed increased expression in chronic myeloid leukemia, and it was found to mechanistically promote the expression of the BCR:ABL fusion gene by demethylating H3K9me1/2 and H3K27me." (PMID 40940894, 2025). "The knockdown of PHF8 sensitized chronic myeloid leukemia cells to imatinib." (PMID 40940894, 2025). "Inhibition of PHF8 activity was found to reduce BCR-ABL1 expression and promote differentiation and inhibit proliferation of chronic myeloid leukemia cells." (PMID 40584293, 2025).
colorectal adenocarcinoma (2 papers, 2023 to 2025). The most common type of colorectal carcinoma. "We found that PHF8 was highly expressed in tumors compared with adjacent normal tissues in colorectal adenocarcinoma patients." (PMID 37454216, 2023). "To examine the functional role of PHF8 in tumor growth in vitro, we deleted Phf8 in mouse models of colorectal adenocarcinoma (CT26 and MC38) using the CRISPR-Cas9 technology." (PMID 37454216, 2023). "In particular, LTR9C and LTR2B expression were anti-correlated with PHF8 expression, suggesting that PHF8 repressed specific ERVs in human colorectal adenocarcinoma." (PMID 37454216, 2023). "Moreover, PHF8 expression is anti-correlated with canonical immune signatures and antiviral immune responses in human colorectal adenocarcinoma." (PMID 37454216, 2023).
glioma (2 papers, 2015 to 2021). A benign or malignant brain and spinal cord tumor that arises from glial cells (astrocytes, oligodendrocytes, ependymal cells). "We identified that miR-101 inhibits the expression of SUV39H1/2 and G9a but enhances the expression of PHF8 in glioma cells." (PMID 25829251, 2015). "For PHF8 and SYMD2, even though reports have confirmed their oncogenic roles in other cancer types, little is known about the function of these biomarkers in glioma." (PMID 33459509, 2021).
neuropathy (2 papers, 2023 to 2024). A disorder affecting the nervous system that manifests with pain, tingling, numbness, and/or muscle weakness. "Blmh loss causes astrogliosis in mice while the loss of histone demethylase Phf8, which controls mTOR signaling, causes neuropathy in mice and humans." (PMID 37718819, 2023).
non-small cell lung carcinoma (2 papers, 2023 to 2025). A group of at least three distinct histological types of lung cancer, including non-small cell squamous cell carcinoma, adenocarcinoma, and large cell carcinoma. "The tumor-promoting function of PHF8 is triggered by the overexpression of oncogenic miR-21, which suppresses the tumor suppressor gene PTEN, leading to tumor growth and invasion in non-small cell lung cancer." (PMID 37218871, 2023). "Indeed, we observed that specific knockdown of HER3 markedly decreased PHF8 expression in TNBC and non-small cell lung cancer cells (data not shown)." (PMID 41198671, 2025).
viral infection (2 papers, 2023 to 2024). "Although histone modifications were found to play a protective role in the body’s defense against viral infections, the functions of jarid2b and phf8 in epigenetic interaction and immune response of teleost fish require further study." (PMID 39211041, 2024). "KEGG analysis revealed that several immune-related pathways, including cytokine-cytokine receptor interaction, virus infection, and host defense pathways, were enriched in the PHF8 low expression group." (PMID 37454216, 2023). "As indicated by KEGG analysis, Phf8 KO CT26 cells exhibited activation of multiple viral infection and antiviral host-defense pathways; however, Phf8 reintroduction preferentially suppressed these responses." (PMID 37454216, 2023).
X-linked mental retardation syndrome (2 papers, 2012 to 2018). "As to PHF8, mutations in this gene cause the X-linked mental retardation syndrome Siderius that includes cleft palate as a common phenotypic feature." (PMID 22723972, 2012).
autism (1 paper, 2021). Persistent deficits in social interaction and communication and interaction as well as a markedly restricted repertoire of activity and interest as well as repetitive patterns of behavior. "Mutations in PHD Finger Protein 8 (PHF8) are also associated with X-linked mental retardation and often accompanied by cleft lip/palate or autism." (PMID 33477877, 2021).
benign prostatic hyperplasia (1 paper, 2016). A non-cancerous nodular enlargement of the prostate gland. "In addition, the levels of PHF8 in benign prostatic hyperplasia, castration-sensitive and castration-resistant specimens are highly correlated with differentiation grade and the highest level of PHF8 was observed in castration-resistant cancers." (PMID 27991916, 2016).
clear cell carcinoma (1 paper, 2022). "In contrast, PHF8 was found to be overexpressed in clear cell carcinoma compared to the other histotypes." (PMID 34991589, 2022).
cleft lip (1 paper, 2018). Congenital defect in the upper lip where the maxillary prominence fails to merge with the merged medial nasal prominences. "Previous genetic studies demonstrated that patients with familial Phf8 mutations display syndromic XLID with cleft lip and palate." (PMID 29317619, 2018).
colon cancer (1 paper, 2024). "In accordance, our data showed that PHF8 was overexpressed and associated with poor prognosis in colon cancer." (PMID 39048555, 2024). "To investigate the mechanism by which CDK5RAP2 S and PHF8 promote EMT in colon cancer, we performed RT-qPCR experiments." (PMID 39048555, 2024). "TNMplot database analysis showed that PHF8 was up-regulated in colon cancer (Tumor) and the expression of PHF8 was higher in metastatic cancer (Metastatic) than in primary cancer (Tumor)." (PMID 39048555, 2024). "Collectively, these data indicate that CDK5RAP2 S specifically interacts with PHF8, and that PHF8 may promote EMT in colon cancer cells." (PMID 39048555, 2024).